PURA (purine rich element binding protein A)
Description:
This is a probable transcription activator that specifically binds the purine-rich single strand of the PUR element located upstream of the MYC gene. May play a role in the initiation of DNA replication and in recombination.
Synonyms: PUR1; PURALPHA; PUR-ALPHA; MRD31; NEDRIHF
Tractability: PROTAC: ubiquitination databases record sites on it; its protein half-life has been measured.
Gene: Protein-coding gene on chromosome 5 (140,107,777 to 140,125,619, forward strand). Ensembl gene ENSG00000185129.
Subcellular location: Nucleus
Gene Ontology:
Molecular function: double-stranded telomeric DNA binding; protein binding; RNA binding; DNA-binding transcription factor activity, RNA polymerase II-specific; DNA-binding transcription factor binding; DNA-binding transcription repressor activity, RNA polymerase II-specific; mRNA regulatory element binding translation repressor activity; purine-rich negative regulatory element binding; RNA polymerase II transcription regulatory region sequence-specific DNA binding; single-stranded DNA binding; DNA binding; DNA-binding transcription factor activity; double-stranded DNA binding; SMAD binding; transcription regulator inhibitor activity
Biological process: negative regulation of transcription by RNA polymerase II; DNA replication initiation; regulation of transcription by RNA polymerase II; dendritic transport of messenger ribonucleoprotein complex; negative regulation of translation
Cellular component: nucleus; chromosome, telomeric region; cytoplasm; dendrite; glutamatergic synapse; neuronal cell body; postsynapse
Genetic constraint (gnomAD): Loss-of-function variants: 0 observed, 21.7 expected, observed/expected ratio (o/e) 0, 90% interval 0 to 0.14. The synonymous counts are far from expectation, so gnomAD's model fits this gene poorly and the ratio says little. Missense variants: 154 observed, 396.34 expected, observed/expected ratio (o/e) 0.39, 90% interval 0.34 to 0.44. Synonymous variants: 231 observed, 182.98 expected, observed/expected ratio (o/e) 1.26, 90% interval 1.13 to 1.41.
Gene-disease validity (ClinGen):
ClinGen rates the evidence that PURA causes each of these diseases.
complex neurodevelopmental disorder (autosomal dominant): Definitive. A disorder that involves more than one phenotype associated with the central nervous system, including but not limited to intellectual disability, autism, and seizures (epilepsy).
Homologues: Orthologues: dog PURA (100% identical), macaque PURA (100% identical), pig PURA (100% identical), rabbit PURA (100% identical), mouse Pura (99% identical), rat Pura (99% identical), zebrafish puraa (80% identical), tropical clawed frog pura (78% identical), zebrafish purab (74% identical), Drosophila melanogaster Pur-alpha (38% identical), Caenorhabditis elegans plp-1 (25% identical), Caenorhabditis elegans plp-2 (16% identical). Paralogues in human: PURB (66% identical), PURG (52% identical).
Diseases named in the same sentence as PURA in open-access papers:
PURA is named in the same sentence as 71 diseases in open-access papers, as found by Europe PMC text mining. Sharing a sentence is not in itself a finding about the gene and the disease. The quoted sentences say what the papers report.
PURA syndrome (15 papers, 2019 to 2026). "Currently, more than 270 different pathogenic variants in the PURA gene have been identified in over 650 patients with confirmed PURA syndrome (personal communication: PURA Foundation Australia)." (PMID 38655849, 2024). "PURA syndrome is a congenital developmental disorder caused by de novo mutations in the PURA gene, which encodes a DNA/RNA-binding protein essential for transcriptional and translational regulation." (PMID 39062627, 2024). "PURA syndrome arises from variants in the PURA gene (purine-rich element binding protein A; OMIM#600473), located at chromosome band 5q31." (PMID 39062627, 2024). "It offers an explanation why even conservative mutations across PURA result in the full penetrance of symptoms in patients with PURA syndrome." (PMID 38655849, 2024). "In a previous study, homology models based on the dmPURA crystal structures were used to predict in silico the effects of PURA syndrome-causing mutations on the structural integrity of the human PURA protein." (PMID 38655849, 2024). "In this study, we experimentally assessed the structure and function of human PURA as well as the impact of representative PURA syndrome-causing mutations on the protein’s integrity." (PMID 38655849, 2024). "This partial loss of PURA mimics the haploinsufficiency in PURA Syndrome patients that harbor heterozygous mutations in the PURA gene." (PMID 36651277, 2023). "Another direct PURA target with potential links to the phenotype of PURA Syndrome patients is the SQSTM1 mRNA encoding the autophagy receptor Sequestome 1 (SQSTM1; also known as p62)." (PMID 36651277, 2023). "In humans, variants and deletions encompassing PURA are associated with PURA-related neurodevelopmental disorders (PURA-NDDs), including the PURA syndrome and 5q31.3 microdeletion syndrome." (PMID 36768582, 2023). "In 2014, mutations in the PURA gene have been linked to the neurodevelopmental disorder PURA Syndrome." (PMID 36651277, 2023). "The RNA-binding protein PURA has been implicated in the rare, monogenetic, neurodevelopmental disorder PURA Syndrome." (PMID 36651277, 2023). "It has been reported that any mutation in the PURA protein causes the full spectrum of the human PURA syndrome." (PMID 35884678, 2022). "Since the description of severe mental retardation in four patients with de novo mutations in the PURA gene, up to date, ~60 different mutations have been characterized in 75 individuals with PURA syndrome." (PMID 35884678, 2022). "Herein, we report on a 3‐year‐old child with severe hypotonia and global developmental delay with a cutaneous phenotype suggestive of CL, in whom WES disclosed a known pathogenic PURA variant, and review all patients with PURA syndrome described so far." (PMID 33275834, 2021). "One of these genes is PURA, for which in 2014 mutations have been shown to cause the neurodevelopmental disorder PURA syndrome." (PMID 33777106, 2021). "Mutations in the human PURA gene cause the neurodevelopmental PURA syndrome." (PMID 38655849, 2024). "Since mitochondrial dysfunctions are associated with various neuronal disorders, it is tempting to speculate that mitochondrial defects caused by PURA haploinsufficiency may contribute to the neurodevelopmental phenotype of PURA Syndrome patients." (PMID 36651277, 2023). "PURA-related neurodevelopmental disorders include Mental Retardation autosomal Dominant 31 (MRD31, #OMIM 616158) or PURA syndrome, caused by heterozygous mutations in the PURA gene or a 5q31.3 deletion affecting completely or partially eliminating the PURA sequence." (PMID 33959609, 2021). "PURA syndrome is caused by heterozygous de novo mutations within the PURA gene." (PMID 33777106, 2021). "When studying the impact of patient mutations on PURA’s subcellular localization, we observed impaired processing body (P-body) association but close-to normal localization to stress granules, indicating a potential importance of P-bodies for PURA syndrome pathology." (PMID 38655849, 2024).
PURA syndrome (continued). "The main difference between the two conditions is that 5q31.3 microdeletion syndrome is caused by a nonrecurrent genomic 5q31.3 deletion, which may encompass all or a part of PURA (10% of affected individuals;), while PURA syndrome is caused by gene variants in the PURA locus." (PMID 36768582, 2023). "Therefore, although it is unclear whether the fistula is associated with the PURA variant, our patient may expand the phenotypic spectrum associated with PURA syndrome." (PMID 35440576, 2022). "At the age of 11 years, the diagnosis of PURA syndrome was confirmed through trio whole exome sequencing (Trio-WES), which revealed a de novo frameshift variant (c.399_400dup; p.Gln134ProfsTer92) of the PURA gene in the proband." (PMID 39062627, 2024). "Future experiments will be necessary to unambiguously clarify the importance of PURA’s localization to stress granules for the etiology of PURA syndrome." (PMID 38655849, 2024). "PURA homozygous knockout mice seem normal at birth, but soon develop neurological symptoms, such as what has been observed in patients with PURA syndrome around 2 weeks after birth." (PMID 36768582, 2023). "Consistent with an important and potentially neuroprotective function of PURA are the reported phenotypes of Pura knock out mouse models and, more recently, symptoms reported for a genetic human disorder, termed PURA syndrome." (PMID 33777106, 2021). "PURA is now included in many developmental disorder and epileptic encephalopathy gene panels, meaning that the diagnosis of PURA syndrome can be made much more readily than when the disorder was first described in 2014." (PMID 33777106, 2021). "Among them, PURα was studied the most, for its implication in fragile × syndrome and PURA syndrome, a disorder characterized by intellectual disability and delayed development of speech and motor skills, such as walking." (PMID 31379499, 2019). "We report the case of a Colombian girl with no relevant medical history who was diagnosed with PURA syndrome at the age of 7, due to a heterozygous mutation located at 5q31.2, specifically the variant c.697_699del (p.Phe233del), in exon 1 of the PURA gene." (PMID 38606370, 2024). "The researchers found that in cells carrying PURA syndrome mutations, PURA failed to move adequately to P-bodies." (PMID 38655849, 2024). "Previously, all patients presenting with symptoms similar to that of PURA syndrome were classified as 5q31.3 microdeletion syndrome, as the disease had not been linked precisely to the PURA locus." (PMID 36768582, 2023). "As PURA Syndrome is described to result from a haploinsufficiency and thereby lowered cellular PURA levels, our findings on PURA-dependent, LSM14A/DDX6-mediated P-body formation could potentially relate to a molecular dysfunction in patients." (PMID 36651277, 2023). "In addition, mice with homozygous deletions of PURA from two independent studies show phenotypes partially resembling patients with PURA Syndrome, including tremor and movement abnormalities." (PMID 36651277, 2023). "Hence, reduced PURA levels, as reported in patients with PURA Syndrome, influence the formation and composition of this phase-separated RNA processing machinery." (PMID 36651277, 2023). "While this study opened the door for an unbiased and systematic understanding of molecular PURA-dependent pathways, it will require more research on both ends, clinical and non-clinical, to convincingly connect our findings with the symptoms in PURA Syndrome patients." (PMID 36651277, 2023). "PURA is implicated in the control of both DNA replication and transcription, and PURA syndrome is noted to include ‘absent speech’ as a feature." (PMID 36117209, 2023). "The clinical features of patients carrying the PURA p.Phe233del variant do not differ from those reported for all patients with PURA syndrome, suggesting that it is difficult to describe reliable genotype–phenotype correlations." (PMID 35440576, 2022).
PURA syndrome (continued). "Thus, the phenotypic expansion, in accordance with data available from electrophysiological studies showing pathological decrements and results from therapeutic interventions showing beneficial effects, led to the re-classification of the PURA syndrome as a PURA-CMS." (PMID 41575592, 2026). "Hence, the aim of this study was to identify target pathways of PURA that could be dysregulated in patients with PURA Syndrome." (PMID 36651277, 2023). "However, now we understand that PURA syndrome, as opposed to the 5q31.3 microdeletion syndrome, is caused by selective PURA heterozygous pathogenic variants in a patient." (PMID 36768582, 2023). "We combine this with molecular and structural insights and provide an update of PURA’s role in neuronal disorders, such as Fragile X-associated tremor ataxia syndrome (FXTAS), the amyotrophic lateral sclerosis (ALS), fronto-temporal dementia (FTD) spectrum disorder, and the PURA syndrome." (PMID 33777106, 2021). "In addition to PURA syndrome, the PURA protein has been found in pathological, RNA-containing foci of patients with the RNA-repeat expansion diseases such as fragile X-associated tremor ataxia syndrome (FXTAS) and amyotrophic lateral sclerosis (ALS)/fronto-temporal dementia (FTD) spectrum disorder." (PMID 33777106, 2021). "We also need to thrive for a better understanding of the role of PURA in non-neural tissues as this will help to elucidate systemic disease processes in patients with PURA syndrome." (PMID 33777106, 2021). "Patients with this disorder, named PURA syndrome, share several symptoms with patients developing the 5q31.3 microdeletion syndrome, suggesting that the lack of PURA accounts for many of the clinical features observed in the 5q31.3 microdeletion syndrome." (PMID 33777106, 2021).
Intellectual disability (8 papers, 2019 to 2026). "Recent studies have also highlighted de novo mutations in PURA, which cause PURA-associated neurodevelopmental disorder characterized by severe intellectual disability, hypotonia, and early-onset spasms." (PMID 41470225, 2025). "Mutations have been identified in the 5’ end of PURA, resulting in a range of symptoms that almost always include neurodevelopmental delay, intellectual disability, hypotonia, and epilepsy." (PMID 39062627, 2024). "PURA first became a candidate for neurodevelopmental disorders when deletions of the genomic region 5q31.2–3, which includes the genes Neuregulin2 and PURA, were reported to correlate with intellectual disability (ID) and other related symptoms." (PMID 33777106, 2021).
HIV-1 infection (6 papers, 2015 to 2026). The type species of lentivirus and the etiologic agent of acquired immunodeficiency syndrome (AIDS). "The modulation of susceptibility to HIV-1 infection, by the targeting of purine-rich element binding protein alpha (Pur-α) mRNA, was also recently demonstrated for miR-15a, miR-15b, and miR-16." (PMID 34947989, 2021). "Moreover, we show that the ivRBPs PURA and its homolog PURB control HIV-1 particle infectivity and engage with several viral proteins and key elements within HIV-1 gRNA, showcasing the importance of ivRBPs for HIV-1 infection." (PMID 41955099, 2026).
amyotrophic lateral sclerosis (5 papers, 2021 to 2024). Amyotrophic lateral sclerosis (ALS) is a neurodegenerative disease characterized by progressive muscular paralysis reflecting degeneration of motor neurons in the primary motor cortex, corticospinal tracts, brainstem and spinal cord. "For example, PURα colocalized with mutant FUS in stress granules to modulate amyotrophic lateral sclerosis (ALS) pathology." (PMID 35945453, 2022). "PURA has been implicated in two different nucleotide-repeat expansion disorders: fragile X-associated tremor/ataxia syndrome (FXTAS) and the disease continuum of C9orf72-mediated amyotrophic lateral sclerosis and fronto-temporal dementia (C9 ALS/FTD)." (PMID 33777106, 2021). "Together with other proteins, PURA forms density granules in diseases related to the RNA repeat expansion disorders, such as fragile X mental retardation protein (FMRP), encoded by FMR1 gene and amyotrophic lateral sclerosis (ALS)/frontotemporal dementia (FTD) spectrum disorder." (PMID 36768582, 2023). "Accordingly, PURA has been implicated as a modulator of neurodegenerative disorders, such as fragile X-associated tremor/ataxia syndrome (FXTAS), and the amyotrophic lateral sclerosis (ALS) frontotemporal dementia spectrum disorder." (PMID 38655849, 2024). "In a cell culture model for amyotrophic lateral sclerosis (ALS), changes in PURA expression modulated the pathological appearances of stress granules and mitigated ALS-related neurotoxicity, indicating a functional importance of PURA for these membrane-less organelles." (PMID 36651277, 2023).
epilepsy (5 papers, 2021 to 2025). A brain disorder characterized by episodes of abnormally increased neuronal discharge resulting in transient episodes of sensory or motor neurological dysfunction, or psychic dysfunction. "In experiments performed by Khalili13, Purα knockout mice developed severe tremors, spontaneous epilepsy and other neurological problems at 2 weeks of age and died 4 weeks after birth." (PMID 34108502, 2021).
breast carcinoma (4 papers, 2016 to 2025). "Most recently, several studies have revealed that PURα is dysregulated in multiple cancers, such as breast cancer (BC) and esophageal squamous cell carcinoma (ESCC)." (PMID 39844051, 2025). "Later, PURα has been identified as a potential tumor suppressor in several cancer types, including glioblastoma (GBM), prostate cancer (PC), and breast cancer (BC)." (PMID 39844051, 2025). "AGPG engaged in a physical interaction with PURα, which in turn freed E2F1 from PURα’s grasp, thereby triggering the activation of E2F1 signaling pathways in ERα-positive breast cancer cells." (PMID 39439957, 2024). "The same as in this report, PURα and E2F1 were co-localized in the nuclear fraction of breast cancer cells, and AGPG disrupted the formation of the PURα/E2F1 complex to activate E2F signaling, facilitating ER-positive breast cancer cell proliferation and endocrine resistance." (PMID 39000020, 2024).
developmental delay (4 papers, 2022 to 2025). "We report on a 15-year-old Japanese female patient with hypotonia and global developmental delay from the neonatal period who was revealed to carry a known pathogenic PURA variant (NM_005859.5:c.697_699del, p.Phe233del) by whole-exome sequencing." (PMID 35440576, 2022). "Here, we report a Japanese female patient with hypotonia and global developmental delay carrying a known pathogenic PURA variant (NM_005859.5:c.697_699del, p.Phe233del)." (PMID 35440576, 2022). "Mutations in PURA may alter normal brain development and impair neuronal function, leading to developmental delay." (PMID 36006904, 2022). "In conclusion, we report on a 15-year-old Japanese female with hypotonia and global developmental delay from the neonatal period that had an unknown cause for many years but was finally revealed to result from the PURA p.Phe233del variant, which was identified by WES." (PMID 35440576, 2022).
esophageal squamous cell carcinoma (4 papers, 2020 to 2025). Esophageal squamous cell carcinoma (ESCC) is a type of esophageal carcinoma (EC) that can affect any part of the esophagus, but is usually located in the upper or middle third. "However, in 2021, Gao discovered high expression of PURα in esophageal squamous cell carcinoma (ESCC) tumors and identified a critical role of PURα in promoting the metastasis of ESCC cells via transcriptional activation of Snail2." (PMID 39844051, 2025).